PELI1 (pellino E3 ubiquitin protein ligase 1)
Diseases named in the same sentence as PELI1 in open-access papers (continued):
Sharing a sentence is not in itself a finding about the gene and the disease.
Sepsis (7 papers, 2015 to 2025). Sepsis is defined as life-threatening organ dysfunction caused by a dysregulated host response to infection. "In conclusion, Peli1 is implicated in sepsis and its progression in various organs and tissues through multiple pathways." (PMID 38179042, 2023). "In the current study, we found that the expression level of PELI1 in PBMCs from sepsis patients was significantly higher than that in PBMCs from healthy individuals." (PMID 41143725, 2025). "We demonstrated that cardiac-specific or global knockout of Peli1 individually induced pro-inflammatory and pro-apoptotic responses in sepsis, which contributed to myocardial inflammation, cell death, and overall cardiac dysfunction." (PMID 37296648, 2023). "It is unclear why CP1KO mice appear to have more significantly hampered cardiac function in sepsis relative to Peli1 total body knockout mice." (PMID 37296648, 2023). "In conclusion, Peli1 has the potential to attenuate the sepsis induced myocardial dysfunction and oxidative stress that accompanies severe sepsis." (PMID 37296648, 2023). "Given these manifold applications, we investigated the role of Peli1 in sepsis using transgenic and knockout mouse models specific to this protein." (PMID 37296648, 2023). "From our data, it is very obvious that both IL-6 and TNF-α levels were significantly elevated in Peli1 global knockout mice after sepsis compared to the other sepsis groups." (PMID 37296648, 2023). "Results are expressed as mean ± S.E.M. Results: AMPEL1Tg/+ prevents sepsis-induced cardiac dysfunction assessed by echocardiographic analysis, whereas global and cardiomyocyte-specific deletion of Peli1 shows significant deterioration of cardiac functions." (PMID 37296648, 2023). "Therefore, the severity is greater when Peli1 is globally knocked out and subjects are exposed to sepsis compared to CP1KO, AMPEl1Tg/+, and even WTCLP." (PMID 37296648, 2023). "Conversely, when Peli1 was knocked out (both globally and in cardiomyocytes alone), there was an increase in inflammatory cytokines, suggesting a potential role for Peli1 in mitigating the inflammatory cascade present in sepsis." (PMID 37296648, 2023). "However, a further detailed study is required with an extended timeline related to sepsis with Peli1 treatment to better understand its in-depth molecular mechanism." (PMID 37296648, 2023). "Peli1 plays a prominent pro-inflammatory role in sepsis as an inflammatory factor." (PMID 38179042, 2023). "Therefore, targeting Peli1 has a significant therapeutic potential for managing sepsis." (PMID 38179042, 2023). "This study describes the role of Pellino-1 (Peli1) in sepsis and functions to determine its potential benefit as a target for ameliorating SIMD in severe sepsis." (PMID 37296648, 2023). "A significant decrease in the expression level of Bax protein was seen in the cardiac AMPEL1Tg/+CLP mice compared to the WTCLP, Peli1−/−, and CP1KO sepsis groups." (PMID 37296648, 2023). "Interestingly, we found that the Peli1 global knockout group showed more IL-6 released in the blood stream when compared to the WTCLP (706.8 ± 43 vs. 483.2 ± 24.01; pg/mL; n = 6; p < 0.0001) and CP1KO sepsis groups (706.8 ± 43 vs. 503.3 ± 10.59; pg/mL; n = 6; p = 0.0002)." (PMID 37296648, 2023).
atherosclerosis (4 papers, 2022 to 2025). A disease characterized by the build-up of fatty material and calcium deposition in the arterial wall resulting in partial or complete occlusion of the arterial lumen. "Peli1 undoubtedly emerges as an important regulator of systemic and local vascular inflammation and which deficiency contributes to atherosclerosis progression linked to destabilization of the atherosclerotic plaques." (PMID 35805095, 2022). "We demonstrate for the first time the role of the E3 ubiquitin ligase Peli1 as an important regulator for inflammatory-associated plaque destabilization in atherosclerosis." (PMID 35805095, 2022). "Considering the importance of chronic inflammation in atherosclerosis, we investigated the impact of Peli1 deficiency on systemic immune mediators." (PMID 35805095, 2022). "Peli1-deficient Apoe−/− mice fed HCD showed also a comparable with Apoe−/− mice atherosclerosis lesion size and lipid accumulation in the aortic roots and the abdominal aorta." (PMID 35805095, 2022). "In the present model of atherosclerosis, hypercholesteremia in Peli1-deficient mice reduced the percentage of FO B cells in the lymph nodes of Peli1 deficient mice, while in line with the previous findings the systemic level of IgG2a has been significantly elevated in Apoe−/−Peli1−/− mice fed HCD." (PMID 35805095, 2022). "In advanced atherosclerosis, Peli1 deficiency appears to induce a multitude of detrimental effects." (PMID 35805095, 2022). "While PELI1 has been linked to immune infiltration in the TIME, prior studies have only focused on lymphoma and atherosclerosis." (PMID 41562077, 2025). "In contrast, Peli1 plays a protective role in other diseases such as atherosclerosis, some infectious diseases, and SLE." (PMID 38179042, 2023). "Peli1 a type of E3 ubiquitin ligase has emerged as a critical regulator of innate and adaptive immunity, however, its role in atherosclerosis remains to be elucidated." (PMID 35805095, 2022). "In the present study, we investigate the role of Peli1, a member of the Peli (Pellino) family of E3 ubiquitin ligases in atherosclerosis pathology." (PMID 35805095, 2022). "The present study provides compelling evidence of the critical function of Peli1 E3 ubiquitin ligase in the pathogenesis of atherosclerosis." (PMID 35805095, 2022). "The present findings indicate that although Peli1 deficiency in Apoe−/− mice in advanced atherosclerosis does not affect atherosclerotic lesion size, it promotes modulation of key features of the plaque stability." (PMID 35805095, 2022).
autoimmune disease (4 papers, 2016 to 2025). A disorder resulting from loss of function or tissue destruction of an organ or multiple organs, arising from humoral or cellular immune responses of the individual to their own tissue constituents. "Conversely, Peli1-deficient mice were susceptible to spontaneous autoimmune disease, which indicated the loss of self-tolerance." (PMID 32352018, 2020). "Peli1 regulates multiple autoimmune diseases with protective and pathogenic roles." (PMID 38179042, 2023). "In fact, Peli1 knockout (KO) mice spontaneously developed autoimmune disease implicating that the Peli1 protein is a negative regulator of T-cell activation." (PMID 27746629, 2016). "This knowledge could provide valuable insights into the therapeutic potential of targeting PELI1 in diseases where macrophage polarization plays a critical role, such as chronic inflammation, tissue repair, and autoimmune diseases." (PMID 41143725, 2025). "Peli1 also differentially regulates several autoimmune diseases." (PMID 38179042, 2023).
chronic obstructive pulmonary disease (4 papers, 2022 to 2025). A chronic and progressive lung disorder characterized by the loss of elasticity of the bronchial tree and the air sacs, destruction of the air sacs wall, thickening of the bronchial wall, and mucous accumulation in the bronchial tree. "Peli1 is pathogenic in several respiratory diseases, notably Chronic obstructive pulmonary disease (COPD), asthma, acute lung injury, and persistent bacterial bronchitis (PBB)." (PMID 38179042, 2023). "According to a previous study, in the chronic obstructive pulmonary disease (COPD) mouse model, inhibiting the expression of PELI1 can reduce senescence-associated secretion phenotypes (SASPs) regulated by p21." (PMID 40735606, 2025).
encephalitis (4 papers, 2020 to 2024). An acute inflammatory process affecting the brain parenchyma. "In the VSV encephalitis model, at least, Peli1 was found to be a negative regulator of type I IFN expression within the CNS." (PMID 33437050, 2021). "Since type I IFN expression and signaling in the CNS are critical for host protection after viral encephalitis, the authors proposed that Peli1-KO mice have better survival than WT mice." (PMID 33437050, 2021). "In addition, Peli1 promotes microglia activation and leads to lethal encephalitis primarily via facilitating WNV replication in the CNS." (PMID 32544190, 2020). "Moreover, Peli1 is emerging as a microglia-specific regulator to participate in the pathophysiological process of experimental autoimmune encephalomyelitis (EAE), West Nile virus (WNV) encephalitis, and subarachnoid hemorrhage (SHA), suggesting causative involvement of Peli1 in neuroinflammation." (PMID 32171293, 2020). "Specifically, Peli1 is emerging as a microglia-specific regulator to participate in the pathophysiological process of experimental autoimmune encephalomyelitis (EAE), subarachnoid hemorrhage (SHA), and West Nile virus (WNV) encephalitis." (PMID 32171293, 2020). "Additionally, PELI1 is progressively becoming acknowledged as a regulator specific to microglia, contributing to the pathological progression of experimental autoimmune encephalomyelitis (EAE), viral encephalitis, West Nile virus (WNV) encephalitis, and subarachnoid hemorrhage (SHA)." (PMID 38338716, 2024). "Mice that do not express Peli1 showed reduced viral titers in the CNS and had increased survival upon a lethal VSV or WNV encephalitis challenge compared to WT mice." (PMID 33437050, 2021).
esophageal cancer (4 papers, 2022 to 2025). A primary or metastatic malignant neoplasm involving the esophagus. "Consistent with this, a comprehensive analysis of transcriptome and methylation data from the Gene Expression Omnibus database revealed that high Peli1 expression in in patients with esophageal cancer is associated with longer overall survival." (PMID 38179042, 2023). "In order to determine the potential function of PELI1 in radiotherapy, we induced a model of esophageal cancer in wild‐type (WT) and Peli1‐deficient mice using 4‐nitroquinoline 1‐oxide (4‐NQO)." (PMID 34738714, 2022). "In oesophageal cancer, PELI1 has been shown to mediate K48 chain polyubiquitination, inhibiting the atypical NF-κB pathway and modulating tumour cell sensitivity to radiotherapy." (PMID 38528516, 2024). "However, in some tumor backgrounds, Peli1 is a beneficial factor with a protective function in antitumor immunity, and promotes radiation therapy sensitivity in esophageal cancer." (PMID 38179042, 2023). "Analysis of normalized TCGA data revealed significant PELI1 upregulation across multiple malignancies, including cholangiocarcinoma (CHOL), esophageal carcinoma (ESCA), kidney renal clear cell carcinoma (KIRC), hepatocellular carcinoma (LIHC), and stomach adenocarcinoma (STAD)." (PMID 41562077, 2025).
experimental autoimmune encephalomyelitis (4 papers, 2016 to 2023). An autoimmune demyelinating disease of the central nervous system that is produced experimentally in animals by the injection of homogenized brain or spinal cord in Freund's adjuvant. "In the present study the overall brain proteomes of Peli1 knock-out mice and wild-type mice were compared prior to experimental autoimmune encephalomyelitis induction, at onset of the disease and at disease peak." (PMID 27746629, 2016). "In the multiple sclerosis disease model, experimental autoimmune encephalomyelitis, Peli1 knock-out led to less activated microglia and less inflammation in the central nervous system." (PMID 27746629, 2016). "In Peli1 knock-out a higher degree of antigen presentation, increased activity of adaptive and innate immune cells and alterations to proteins involved in iron metabolism were observed during experimental autoimmune encephalomyelitis." (PMID 27746629, 2016). "The experimental autoimmune encephalomyelitis with mice lacking PELI1 found that antigen presentation was enhanced, adaptive and innate immune cells were more active, and proteins involved in iron metabolism were altered." (PMID 36593453, 2023).
lung adenocarcinoma (4 papers, 2016 to 2025). A carcinoma that arises from the lung and is characterized by the presence of malignant glandular epithelial cells. "Therefore, PELI1 acts as an oncoprotein in lung adenocarcinoma to regulate tumor development." (PMID 34738714, 2022). "In contrast, protein-level data demonstrated PELI1 downregulation in uterine corpus endometrial carcinoma (UCEC), lung adenocarcinoma (LUAD), and head and neck squamous cell carcinoma (HNSC)." (PMID 41562077, 2025).
lymphoma (4 papers, 2017 to 2025). A malignant (clonal) proliferation of B- lymphocytes or T- lymphocytes which involves the lymph nodes, bone marrow and/or extranodal sites. "High Peli1 expression in lymphoma is associated with frequent bone marrow involvement and shorter relapse-free survival." (PMID 38179042, 2023). "Peli1 overexpression, implicated in lymphoma progression, is significantly elevated in various lymphomas." (PMID 38179042, 2023). "In this regard, future research should examine the relationships between Peli1 and pathogenic conditions, such as lymphomas, and determine how Peli1 is differentially expressed in different tissues and cell types." (PMID 28410192, 2017). "A study focusing on the Bcl-6-dependent risk stratification of DLBCL based on Peli1 nuclear expression highlighted the potential role of Peli1 and Bcl-6 in assessing DLBCL risk Peli1 expression is highly elevated in high-grade lymphomas but significantly reduced in low-grade lymphomas." (PMID 38179042, 2023). "Elevated Peli1 expression induces lymphoma development by facilitating B-cell lymphoma 6 (BCL6) ubiquitination through K63 linkage and promoting the constitutive activation of the post-BCL6 B-cell signaling pathway." (PMID 38179042, 2023). "Peli1 expression may be a valuable prognostic indicator for patients with lymphomas, especially those with diffuse large B cell lymphoma (DLBCL)." (PMID 38179042, 2023). "This paradoxical role of Peli1 in different lymphomas may partly explain the differential expression of Peli1 in distinct grades of lymphomas and provide insights into developing t of personalized medical treatments for lymphomas." (PMID 38179042, 2023). "Peli1 expression positively correlates with the MYC, BCL6, BCL2, and MUM1 expression in lymphomas." (PMID 38179042, 2023). "As Peli1-transgenic (Tg) mice develop tumours in various organs including the spleen, splenocytes were isolated from Peli1-Tg mice that displayed splenic plasmacytoid differentiation and lymphomas, and from control littermate non-Tg mice that had normal splenic features." (PMID 28410192, 2017).
myocardial infarction (4 papers, 2021 to 2023). Gross necrosis of the myocardium, as a result of interruption of the blood supply to the area, as in coronary thrombosis. "Due to the diversity of Peli1 substrates and the wide range of biological functions in which Peli1 is involved, we also noted that Peli1 is primarily pathogenic in some diseases such as cancer, myocardial infarction, and AD." (PMID 38179042, 2023). "We have observed that overexpression of mammalian Pellino-1 (Peli1), an E3 ubiquitin ligase, causes inhibition of apoptosis, oxidative stress, and preservation of cardiac function in a myocardial infarction model." (PMID 37296648, 2023). "Our laboratory has thoroughly studied the role of the Peli1 protein as a mediator of angiogenesis and ischemic remodeling following myocardial infarction and hind limb ischemia." (PMID 37296648, 2023). "Inhibiting BIK autophagic degradation by Peli1 promotes apoptotic pathway activation by inhibiting BCL2, which increases myocardial infarction and contributes to cardiac dysfunction." (PMID 38179042, 2023).
psoriasis (4 papers, 2019 to 2023). An autoimmune condition characterized by red, well-delineated plaques with silvery scales that are usually on the extensor surfaces and scalp. "Although its pathogenic role in MS and psoriasis is well- recognized, Peli1 plays a protective role against SLE." (PMID 38179042, 2023). "Peli1 plays a pathogenic role in psoriasis and acts as an inflammatory modulatior in EAE, primarily promotes inflammation but inhibiting excessive inflammation." (PMID 38179042, 2023). "Thus, Peli1-mediated hyperactivation of keratinocytes triggers pathogenic hyperactivation of T cells and subsequent cross-talk between keratinocytes and T cells during the pathogenesis of skin inflammation and psoriasis lesions." (PMID 32873845, 2020). "To dissect the pathways by which Peli1 expression induces the development of psoriasis, we utilized the adoptive transfer function of congenic mouse bone marrow (BM) cells." (PMID 32873845, 2020). "Increased Peli1 expression is strongly correlated with the immunopathogenesis of psoriasis by activating hyperproliferation of keratinocytes in the S and G2/M phases of the cell cycle and promoting chronic skin inflammation." (PMID 32873845, 2020). "To gain insight into the molecular pathogenesis of Peli1-induced psoriasis, we analyzed a panel of key inflammation-related genes usually activated during psoriasis using an RT2 profiler PCR array." (PMID 32873845, 2020). "A strong upregulation of Peli1 expression was observed in the entire epidermis, including in infiltrated immune cells and blood vessels of skin lesions derived from psoriasis patients compared with those derived from healthy skin." (PMID 32873845, 2020). "The expression of Peli1 was barely detectable in most healthy human skin samples, while it was highly upregulated in lesional skin samples derived from psoriasis patients." (PMID 32873845, 2020). "To further analyze the Peli1 protein expression profile in chronic inflammatory skin diseases, we collected skin samples from psoriasis patients and heathy controls and compared the Peli1 levels." (PMID 32873845, 2020). "Peli1 activation in T cells is insufficient to trigger psoriasis-like disease, while T cells are indispensable for establishing the disease." (PMID 32873845, 2020). "However, in skin plaques and lesions obtained from psoriasis patients, Peli1 expression was upregulated in the cytoplasm and a few nuclei of the entire layer of epidermal keratinocytes except the stratum corneum." (PMID 32873845, 2020). "However, the overexpression of Peli1 in T cells was insufficient to trigger psoriasis, while T cells were indispensable for disease manifestation." (PMID 32873845, 2020). "Although TNFα-targeting and IL-17a-targeting drugs have been found to be effective, a targeting strategy that inhibits Peli1 might be a more powerful approach to treat psoriasis." (PMID 32873845, 2020). "We further examined whether cytokines and chemokines mediated the pathogenesis of psoriasis by overexpression of Peli1 in keratinocytes." (PMID 32873845, 2020). "Therefore, we investigated the molecular mechanism underlying the activation of keratinocyte proliferation and the development of psoriasis induced by overexpression of Peli1." (PMID 32873845, 2020). "In this study, we found that the Pellino1 (Peli1) ubiquitin E3 ligase is activated by innate pattern-recognition receptors (PRRs), such as Toll-like receptors (TLRs), and is highly upregulated in human psoriatic skin lesions and murine psoriasis-like models." (PMID 32873845, 2020). "Peli1 expression is enhanced in the epidermis of psoriasis lesions, and doxy-inducible Peli1tg mice spontaneously develop psoriatic inflammation, which depends on Peli1 overexpression in radioresistant cells, with increased expression levels of IL-17 and IL-22 in the skin." (PMID 31156649, 2019). "Moreover, Peli1 is possibly involved in the development of psoriasis." (PMID 31156649, 2019).